CD24 (CD24 molecule)
Diseases named in the same sentence as CD24 in open-access papers (continued):
Sharing a sentence is not in itself a finding about the gene and the disease.
acute renal failure (7 papers, 2009 to 2025). "In vivo studies have demonstrated the ability of CD133+CD24+ cells to repair damaged kidney tubules and promote recovery of kidney function when these cells are injected into a mouse with acute kidney injury." (PMID 40141116, 2025). "CD133+CD24+ renal tubular progenitor cells play a crucial role in the repair and regeneration of renal tubules after acute kidney injury." (PMID 40141116, 2025). "When injected into mice with acute renal failure, CD24+CD133+ progenitors purified from embryonic tissues regenerate cells of different portions of the nephron, reduce tissue necrosis and fibrosis, and improve renal function." (PMID 19739254, 2009). "When injected intravenously in SCID mice that had acute renal failure (ARF), CD24+CD133+ renal progenitors regenerated tubular structures in different portions of the nephron and also reduced the morphological and functional kidney damage." (PMID 19558670, 2009).
diffuse large B-cell lymphoma (7 papers, 2015 to 2024). "Contrarily, in diffuse large B-cell lymphoma (DLBCL), CD24 mAb treatment was less successful than CD47 mAb treatment." (PMID 38279998, 2024). "CD24 antibody treatment improved the phagocytosis of patient-derived mantle cell lymphoma (MCL) cells by macrophages but was less effective in diffuse large B-cell lymphoma (DLBCL)." (PMID 37894750, 2023). "Conversely, CD24 expression did not correlate with survival in diffuse large B-cell lymphoma (DLBCL), whereas CD47 did." (PMID 35625912, 2022). "Interestingly, CD24 acts as a complementary signal of CD47 and appears to have inversely correlated expression in human diffuse large B‐cell lymphoma." (PMID 33449453, 2021). "For diffuse large B-cell lymphoma (DLBCL), the most common type of NHL in adults, CD24 expression was also reported, although in this case, high expression of CD24 mRNA correlated with better response to R-CHOP in activated B cells (ABC)-DLBCL, a specific subtype of DLBCL patients." (PMID 35625912, 2022).
esophageal cancer (7 papers, 2016 to 2025). A primary or metastatic malignant neoplasm involving the esophagus. "Another study found that individuals with esophageal cancer who had high CD24 mRNA expression had a better outcome after chemoradiotherapy." (PMID 38279998, 2024). "Taken together, these findings provide evidences that esophageal cancer cell lines are heterogeneous with regard to CD24 expression." (PMID 28611669, 2017). "In addition, through mining TCGA esophageal cancer data, we found that CD24 expression was significantly upregulated in esophageal carcinoma tissues." (PMID 38168654, 2024). "Our results also suggest that CD24 might have prognostic and therapeutic implications for the treatment of esophageal cancer, and that celecoxib could be evaluated as a possible candidate for combined chemotherapy with 5-FU in the treatment of esophageal cancer." (PMID 28611669, 2017). "According to another study, SIM2 upregulates CD24 and cytokeratin 4 (CK4), which are prognostic indicators for chemoradiotherapy and surgery in esophageal cancer." (PMID 38279998, 2024). "Our observations demonstrate that administration of the chemotherapeutic 5-FU leads to an increase in CD24 marker expression in esophageal adenocarcinoma cell lines, which may be related to the stem cell phenotype, as suggested by its increased expression in esophageal cancer spheres." (PMID 28611669, 2017). "CD24 and CK4 could be predictive biomarkers for the effectiveness of chemoradiotherapy in esophageal cancer." (PMID 40070828, 2025). "CD24 staining intensity in esophageal cancer cells was very heterogeneous; that is, not all of the tumor cells displayed similar levels of protein expression." (PMID 28611669, 2017).
head and neck cancer (7 papers, 2014 to 2023). A primary or metastatic malignant neoplasm affecting the head and neck. "In the head and neck cancer field, the expression of CD24 was found to be associated with unfavorable outcomes in laryngeal cancer patients." (PMID 38138858, 2023). "We further aimed to seek if head and neck cancer patients with high CD24 levels had certain adverse features or poorer outcomes." (PMID 38138858, 2023). "Materials and Methods: CD24/CD11b expression in peripheral blood leukocytes (PBLs) of head and neck cancer patients and matched healthy controls was analyzed via flow cytometry." (PMID 38138858, 2023). "Further work in a much larger patient cohort will firmly establish the significance of CD24 as a predictive indicator for cisplatin resistance in head and neck cancers." (PMID 27276062, 2016). "Overall, based on the strength of further analysis, CD24 presents a strong rationale to be utilized as a predictive indicator to stratify head and neck cancer patients for platinum-based therapy." (PMID 27276062, 2016). "The immunophenotype CD44+CD24- has been used to identify cancer stem-like cells in head and neck cancers." (PMID 25823923, 2015). "These associations were further established in head and neck cancer cell lines: CD24+ cells possessed stemness characteristics of self-renewal and differentiation, a higher cell invasion in vitro and made a higher number of colonies in collagen gels compared to CD24− HNSCC cells." (PMID 38138858, 2023). "To explore whether these EpCAM+Vim+CD24+ cells in the stroma may in fact be non-tumour cell types, we analysed a published scRNAseq dataset for human head and neck cancer." (PMID 37975646, 2023).
ischemic stroke (7 papers, 2021 to 2025). A stroke disorder caused by obstruction of blood flow to the brain, due to thrombotic (local blood clot formation) or embolic (due to a blood clot or other material traveling from another site) event. "SPRC has been applied to treat ischemic stroke, and its potential association with CD24 has been studied." (PMID 39953809, 2025). "The treatment of SPRC on ischemic stroke is associated with CD24 via CBS/H2S pathway." (PMID 39953809, 2025). "In this study, we have explored innovative new therapies for ischemic stroke and focused on the correlation between neuroinflammation mechanism of ischemic stroke and the immune checkpoint inhibitor CD24." (PMID 39953809, 2025). "For the first time, we have shown that CD24 is a very promising target for treating ischemic stroke." (PMID 39953809, 2025). "In the view of these, we finally revealed that the new mechanism of ischemic stroke treatment of SPRC is associated with the CBS/H2S/CD24/Iκ‐Bα/NF‐κB inflammatory pathway and CBS/H2S/CD24/Src/Fak/Pyk2 migration pathway." (PMID 39953809, 2025). "Here, to explore the role of CD24 that plays in ischemic stroke, mechanism studies have been performed both in vitro and in vivo to verify the CD24‐mediated inflammation and migration." (PMID 39953809, 2025). "In our study, to explore the function of CD24 in ischemic stroke more quickly, we chose to use siRNA to knockdown CD24 instead of using knockout mice." (PMID 39953809, 2025). "In conclusion, this study shows that CD24 may be a potential innovative target of ischemic stroke for alleviating neuroinflammation via NF‐κB pathway and Src pathway." (PMID 39953809, 2025). "Therefore, SPRC can also promote the migration ability of M2 microglia by regulating CD24/Src/Fak/Pyk2 pathway to alleviate ischemic stroke." (PMID 39953809, 2025). "Additionally, SPRC has been used to treat ischemic stroke, and its potential relationship with CD24 has been investigated." (PMID 39953809, 2025). "Additionally, the potential relationship between the H2S donor, S‐propargyl‐cysteine (SPRC) and CD24 in ischemic stroke should be revealed." (PMID 39953809, 2025). "CD24 may be a potential innovative target of ischemic stroke for alleviating neuroinflammation via NF‐κB pathway and Src pathway." (PMID 39953809, 2025). "SPRC reduces inflammation in ischemic stroke by regulating the CD24/Iκ‐Bα/NF‐κB inflammatory signaling pathway and improves the migration ability of M2 microglia via CD24/Src/Fak/Pyk2 signaling pathway, which further alleviates the inflammatory response at the lesion." (PMID 39953809, 2025). "The MR analysis outcome revealed that CD24 on switch memory B cell (OR = 1.03, 95% CI: 1.001-1.067, p = 0.041) and CD4 on CD39+ CD4+ Treg (OR = 1.03, 95% CI: 1.002-1.054, p = 0.031) were weakly associated with an increased risk of ischemic stroke." (PMID 38562935, 2024). "So CD24 may be also a very potential neuroprotective agent of ischemic stroke." (PMID 39953809, 2025). "In ischemic stroke models, SPRC upregulated cluster of differentiation 24 (CD24) expression via the CBS/H2S signaling pathway, suppressing NF-κB and enhancing src/focal adhesion kinase/proline-rich tyrosine kinase 2 (Src/Fak/Pyk2)-dependent microglial migration." (PMID 41465271, 2025). "All the results of these studies have demonstrated that CD24 could negatively regulate neuroinflammation and promote the migration of M2 in BV2 cells, suggesting that CD24 is potentially an innovative therapeutic target of ischemic stroke." (PMID 39953809, 2025).
metastasis (7 papers, 2013 to 2025). The spread or migration of cancer cells from one part of the body (where they first appeared) to another. "Our meta-analysis indicated that overexpression of CD24 in GC was not only associated with tumor exterior expansion, lymph node metastasis and advanced TNM stage, but also was a biomarker for poor prognosis." (PMID 25503963, 2014). "The studies correlated the higher expression of CD24 with larger tumor size, axillary lymph node metastasis, and HER2+ status." (PMID 40821783, 2025). "What is worth further thinking about is whether we can block the expression of CD24 in CRC in some way to inhibit the proliferation of tumor cells and prevent lymph node metastasis, to provide new ideas for clinical diagnosis and treatment to improve the prognosis of patients with CRC." (PMID 35938128, 2022).
pterygium (7 papers, 2009 to 2021). A wedge-shaped fibrovascular lesion arising from the bulbar conjunctiva and extending to the cornea. "This DNA methylation pattern was consistent with reduced levels of TGM-2, as well as increased levels of MMP-2 and CD24 proteins, contributing to fibroblastic and neovascular changes associated with pterygium formation." (PMID 31976085, 2019). "In our study, we found that critical CpG islands associated with the MMP-2 and CD24 genes were demethylated in pterygium, whereas TGM-2 gene sequences were over-methylated." (PMID 21359202, 2011). "In pterygium, the elevated CD24 expression may cause increased proliferation, motility and invasiveness of pterygium epithelial cells and fibroblasts." (PMID 21359202, 2011). "In this study, we demonstrate a significant increase in both MMP-2 and CD24 transcript and protein levels in pterygium tissue, with less methylation in the corresponding genomic sequences." (PMID 21359202, 2011). "MMP-2 and CD24 transcripts however, were upregulated 2.44±0.52 fold and 2.03±0.22 fold (p<0.05), respectively in pterygium compared to normal conjunctiva." (PMID 21359202, 2011). "We have previously investigated the genes specifically involved in wound healing mechanisms such as TGM-2, MMP-2, and CD24 in pterygium." (PMID 21359202, 2011). "Immunofluorescent staining detected the presence of TGM-2, MMP-2, and CD24 in human conjunctiva and pterygium tissue." (PMID 21359202, 2011). "The methylation status at the promoters of TGM-2, MMP-2, and CD24 genes was significantly different between pterygium and uninvolved conjunctiva samples in at least one CpG unit." (PMID 21359202, 2011). "Studies in the regulation of cell adhesion by CD24 and mucous processing pathways are required to understand pterygium formation." (PMID 19272163, 2009). "Besides our data, the literature reviews showed the aberrant DNA methylation and decreased expression of P16, Ecadherin, TGM 2, MMP2, and CD24 genes in pterygium." (PMID 26942001, 2016). "TGM-2, MMP-2, and CD24 gene transcripts were detected in conjunctiva and pterygium tissues." (PMID 21359202, 2011). "Methylation levels of TGM-2, MMP-2, and CD24 in pterygium and conjunctiva." (PMID 21359202, 2011). "Immunofluorescence showed strong expression of keratin-6A in all layers, especially the superficial layers, of pterygium epithelium, but absent in the control, with up-regulation and nuclear accumulation of the cell adhesion molecule CD24 in the pterygium epithelium." (PMID 19272163, 2009). "Recently, a cell adhesion molecule that has never been previously associated with pterygium, CD24, was reported to be upregulated and localized in the nuclei in pterygium epithelium which suggest that cell adhesion properties may be disrupted." (PMID 21359202, 2011). "For instance, the gene expression of pterygium was compared to that of normal autologous conjuntiva, finding a significant increase of fibronectin, CD24, MIP-4, and NGAL in the pterygium lesions." (PMID 22724003, 2012). "A recent paper has shown that pterygium presents aberrant DNA methylation patterns in regions close to matrix remodelling genes such as TGM-2, MMP-2 and CD24." (PMID 22724003, 2012). "Here, we report for the first time the role of methylation in the pathogenesis of pterygium, by profiling the methylation status of TGM-2, MMP-2, and CD24 gene promoters and the effect of methylation in cultured ocular surface cells." (PMID 21359202, 2011). "Our results show that protein expression levels for keratin 6, CEACAM5, CD24, MSMB and MUC5AC were increased, whereas NR4A2 and IGFBP3 were reduced in pterygium, consistent with the transcript changes detected by the microarray analysis." (PMID 19272163, 2009). "Genes up-regulated in pterygium include fibronectin (FN1), CEACAM5 (CEA), CD24, SPARC, MSMB and TFF1." (PMID 19272163, 2009).
pterygium (continued). "This raises the possibility that critical DNA demethylation may facilitate transcription factor(s) downstream of CSF2 to bind to regulatory sequences of CD24 and MMP-2, with a consequential increase in Wnt/β-catenin signaling, which has been previously reported in pterygium." (PMID 21359202, 2011). "Other up-regulated proteins like small proline rich protein 1B (SPRR1B), CD24, S100 calcium binding protein, SPARC, TFF1, SPRR1B and SERPINB13 also govern the wound healing process and cornification of epithelium, again, supporting the hypothesis of aberrant wound response in pterygium." (PMID 19272163, 2009).
small cell lung carcinoma (7 papers, 2003 to 2025). Small cell lung cancer (SCLC) is a highly aggressive malignant neoplasm, accounting for 10-15% of lung cancer cases, characterized byrapid growth, and early metastasis. "For example, Barbara A. Froesch attempted to use the anti-CD24 antibody SWA11 to transport doxorubicin to human small cell lung cancer tumor lesions." (PMID 28881644, 2017). "We found CD24 expression in 45% (five out of 11) of the cell lines: two adenocarcinoma cell lines (two out of six), two small cell lung cancer cell lines (two out of four) and one squamous cell cancer cell line (one out of one)." (PMID 12610508, 2003).
brain tumor (6 papers, 2014 to 2026). "Treatment with mitoxantrone as an immunogenic cell-death-inducing cytostatic agent led to a dose-dependent reduction in cell viability and cell surface CD24 levels in both murine and human brain tumor cell cultures." (PMID 41606146, 2026). "Future studies are needed to explore whether CD24, CD47, or CD276 (B7H3) inhibitors would constitute alternative immunotherapy approaches in CMMRD‐derived brain tumors." (PMID 40880425, 2025).
colorectal tumors (6 papers, 2013 to 2022). "CD24, a membrane surface glycosyl-phosphatidyl-inositol-(GPI)-anchored protein, is overexpressed in 90% of colorectal tumors and has been implicated in inflammatory bowel disease (IBD)." (PMID 33065994, 2020). "Growth inhibition by inducting apoptosis following CD24-blockade has also been demonstrated in CD24-expressing colorectal tumors in vivo." (PMID 33260974, 2020). "CD44+/CD24+ populations obtained from colorectal tumors can initiate growth of colonospheres in vitro and colorectal tumors in vivo, and similar cells exhibit TIC activity across a variety of solid tumors." (PMID 30197752, 2018). "Although we only used a small patient cohort in this study, nevertheless we saw a clear correlation between downregulation of Pdcd4 and miR-34a and enhanced expression of miR-21, CD24 and Src in the resected colorectal tumor samples compared to normal tissue." (PMID 23533633, 2013). "To validate this tumor-specific fibroblast infiltration, we analyzed the expression of stromal cell subtype markers CD24, CD26, NT5E, FAP, and FGFR2 in colorectal tumor and non-malignant large intestine samples by flow cytometry." (PMID 35365629, 2022).
liver fibrosis (6 papers, 2016 to 2023). "Analysis of clinical samples from patients with liver fibrosis also showed a huge abundance of endogenous CD24+LCN2+ cells in ductular reaction foci." (PMID 37784089, 2023). "We previously reported that miR-21 inhibition reduces liver fibrosis by inducing the apoptosis of CD24+ progenitor cells, confirming a major role of these cells in fibrogenesis." (PMID 37296834, 2023). "Using an antibody against CD24 for immunofluorescence, CD24-positive cells were observed in the samples of liver fibrosis but were undetectable in samples of normal liver." (PMID 33859762, 2021). "The in vivo administration of HACY not only induced the conversion of mature hepatocytes (MHs) to CD24+ progenitor cells but prevented the activation of HSCs, thus leading to enhanced improvement of liver fibrosis in CCL4-treated mice." (PMID 33859762, 2021). "Collectively, these results showed that CD24+ progenitor cells existed in human liver fibrosis tissues." (PMID 33859762, 2021). "As an example, LNA-anti-miR-214 had a preventive effect for hepatic fibrosis, while inhibition of miR-21 reduced liver fibrosis through reduction of CD24+ liver progenitor cells." (PMID 29337905, 2018). "The canonical pathway Hepatic Fibrosis/Activation of Hepatic Stellate Cells was the pathway most significantly represented in all three groups (CD24 Up, CD24 Down, and TGFβ3)." (PMID 26788063, 2016). "The administration of HACY, which allowed the induction of endogenous CD24+ progenitor cells and the inactivation of HSCs, exerts beneficial effects in the treatment of liver fibrosis by re-establishing a balance favoring liver regeneration while preventing fibrotic responses." (PMID 33859762, 2021). "In clinical samples of liver fibrosis, CD24+CK19+/CD24+SOX9+ ductular reactive cells were abundantly found in regions of ductular reaction, suggesting the activation and expansion of ductular reactive cells." (PMID 37784089, 2023). "The expression of both CD24 and SOX9 was identified in our study to strongly correlate with liver fibrosis progression and was specifically elevated in fast-progressor NAFLD patients." (PMID 37296834, 2023). "In this study, we reported that the transplantation of HepLPCs, with high levels of CD24 expression, effectively attenuated CCL4-induced liver fibrosis." (PMID 33859762, 2021). "Meanwhile, further studies are necessary to establish whether CD24+LCN2+ LPCs, a major LPC type in ductular reaction, have a ‘reprogramming competence’ to reduce hepatocyte and biliary epithelial cell plasticity (like hepPDs and TLPC) during liver fibrosis and NASH." (PMID 37784089, 2023).